LOX (lysyl oxidase)
Description:
Responsible for the post-translational oxidative deamination of peptidyl lysine residues in precursors to fibrous collagen and elastin. Regulator of Ras expression. May play a role in tumor suppression. Plays a role in the aortic wall architecture (By similarity).
Synonyms: AAT10
Tractability: Small molecule: a high-quality ligand is known. Antibody: UniProt places it where antibodies can reach, with high confidence; its Gene Ontology location is reachable by antibodies, with high confidence; UniProt predicts a signal peptide or a membrane-spanning region. PROTAC: a small molecule that binds it is known.
Target class: Enzyme; Oxidoreductase
Gene: Protein-coding gene on chromosome 5 (122,063,195 to 122,078,634, reverse strand). Ensembl gene ENSG00000113083.
Subcellular location: Secreted; Secreted, extracellular space
Subcellular location (Human Protein Atlas): Endoplasmic reticulum; Predicted to be secreted
Pathways (Reactome):
Extracellular matrix organization: Crosslinking of collagen fibrils; Elastic fibre formation
Gene Ontology:
Molecular function: collagen binding; molecular adaptor activity; protein binding; protein-lysine 6-oxidase activity; small molecule binding; copper ion binding; oxidoreductase activity, acting on the CH-NH2 group of donors, oxygen as acceptor
Biological process: peptidyl-lysine oxidation; blood vessel morphogenesis; collagen fibril organization; platelet-derived growth factor receptor-beta signaling pathway; protein modification process; elastic fiber assembly; response to hormone; response to steroid hormone; response to xenobiotic stimulus
Cellular component: extracellular region; elastic fiber; extracellular matrix; collagen trimer
Genetic constraint (gnomAD): Loss-of-function variants: 10 observed, 33.74 expected, observed/expected ratio (o/e) 0.3, 90% interval 0.18 to 0.5. The upper end of that interval is the gene's LOEUF score, 0.5, which puts it in group 2 of 6, group 1 being the genes least tolerant of losing a copy. Missense variants: 462 observed, 459.76 expected, observed/expected ratio (o/e) 1, 90% interval 0.93 to 1.09. Synonymous variants: 226 observed, 194.71 expected, observed/expected ratio (o/e) 1.16, 90% interval 1.04 to 1.3.
Gene-disease validity (ClinGen):
ClinGen rates the evidence that LOX causes each of these diseases.
familial thoracic aortic aneurysm and aortic dissection (autosomal dominant): Strong. A rare genetic vascular disease characterized by the familial occurrence of thoracic aortic aneurysm, dissection or dilatation affecting one or more aortic segments (aortic root, ascending aorta, arch or descending aorta) in the absence of any other associated disease.
Homologues: Orthologues: chimpanzee LOX (99% identical), macaque LOX (98% identical), pig LOX (93% identical), dog LOX (91% identical), rabbit LOX (88% identical), mouse Lox (86% identical), rat Lox (85% identical), tropical clawed frog lox (68% identical), zebrafish loxa (63% identical). Paralogues in human: LOXL1 (51% identical), LOXL3 (34% identical), LOXL2 (33% identical), LOXL4 (32% identical), DMBT1 (15% identical), CD163L1 (14% identical), SSC4D (13% identical), PRSS12 (13% identical), CD163 (13% identical), SCART1 (12% identical), SSC5D (12% identical), CD6 (12% identical), and 3 more.
Diseases named in the same sentence as LOX in open-access papers:
LOX is named in the same sentence as 333 diseases in open-access papers, as found by Europe PMC text mining. Sharing a sentence is not in itself a finding about the gene and the disease. The quoted sentences say what the papers report.
breast carcinoma (256 papers, 2007 to 2025). "LOX is also associated with mammary cancer bone metastasis through leading to osteolytic lesion formation." (PMID 39792296, 2025). "Treatments targeting LOX can decrease matrix stiffness and potentially decrease breast cancer risk and aggressiveness." (PMID 39202236, 2024). "In vitro studies, primarily in breast cancer, have implicated catalytically active LOX in the promotion of cancer cell migration." (PMID 35804902, 2022). "Different microarray studies have shown an association between tumor hypoxia levels and LOX expression in tumors such as breast cancer and head and neck cancer." (PMID 36497411, 2022). "In conclusion, this study is among the first to examine genetic variants in genes involved in the COX- and LOX-related inflammatory pathways with breast cancer risk among both White and Black women." (PMID 34249719, 2021). "Nevertheless, this study investigates the role of COX and LOX genetic variants in a large number of Black women, which addresses the unmet need to improve representation of Black populations in genomic breast cancer studies." (PMID 34249719, 2021). "Lysyl oxidase (LOX) secretion has been implicated in breast cancer, where under hypoxic conditions the ECM-modifying enzyme promotes osteolytic lesions." (PMID 33659922, 2021). "In cancer biology, hypoxia-inducible factor induces LOX expression, which contributes to hypoxic metastasis in breast cancer and is also associated with a poor prognosis and invasion in lung cancer." (PMID 31921422, 2020). "The expression of lysyl oxidase (LOX) by the breast cancer cells causes cross-linking of collagen fibers that in turn increases matrix tension." (PMID 29874869, 2018). "Although strong evidence indicates LOX promotes bone metastasis in patients with breast cancer, the association between LOX and prognosis in ER– breast cancer patients remained unclear." (PMID 27147578, 2016). "LOX overexpression is reported to be specifically associated with bone relapse in ER– breast cancer patients." (PMID 27147578, 2016). "High LOX expression is reportedly associated with an increased recurrence rate and decreased overall survival in breast cancer, prostatic cancer, renal cell cancer, head and neck squamous cell cancer and gastric cancer." (PMID 26882568, 2016). "We noted several similarities of the G473A SNP and LOX expression with respect to the association with breast cancer survival." (PMID 25141126, 2014). "Potential variations in LOX expression associated with well-established clinical and histopathological characteristics of breast cancer were visualized with boxplots, and their significance assessed with unpaired, two-sided t-tests." (PMID 25141126, 2014). "The G473A polymorphism (rs1800449) results in the Arg158Gln amino acid substitution in the LOX propeptide, compromises its tumour suppressive activity, and was associated with an increased breast cancer risk in a Chinese Han population." (PMID 25141126, 2014). "Dominant, recessive and log-additive inheritance models for the association of LOX G473A genotypes with breast cancer risk in the study population and in clinically relevant subgroups were analysed." (PMID 25141126, 2014). "In the first hospital-based case-control study in European women, we aimed at investigating the association of LOX expression and the G473A polymorphism with breast cancer risk and survival in unselected and estrogen receptor (ER) negative patients." (PMID 25141126, 2014). "Previous studies identified increased expression and secretion of LOX from tumor cells exposed to physiological levels of hypoxia as well as association of LOX with metastasis and poor survival in mammary carcinoma and head and neck cancer patients." (PMID 25052686, 2014). "Association of the LOX G473A polymorphism with breast cancer risk in the indicated inheritance models and subgroups." (PMID 25141126, 2014).
breast carcinoma (continued). "Taken together, these studies indicate that LOX-PP can directly associate with CIN85 in breast cancer cells." (PMID 24167568, 2013). "Of these genes, LOX, which encodes Lysyl oxidase, is essential for hypoxia-induced metastasis and it was reported that breast cancer cell metastasis can be attenuated by lysyl oxidase inhibitors." (PMID 23497265, 2013). "There may be a regulation between these two proteins, since mutations in HIFs can increase LOX expression, creating uncontrolled growth in breast cancer." (PMID 41263153, 2025). "Notably, bioinformatics analysis has identified LOX as a key gene associated with breast cancer metastasis." (PMID 39247609, 2024). "In this study, lysyl oxidase (LOX) was identified as one of most highly upregulated (>2.25-fold) secreted proteins associated with osteotropism in hypoxia-induced secretome release from MDA-MB-231 Bone Tropic breast cancer cell lines." (PMID 33708620, 2021). "Lysyl oxidase has been implicated in incidence of mammary tumors in bitches." (PMID 32542505, 2020). "Importantly, several studies have demonstrated that LOX is associated with breast cancer bone metastasis." (PMID 30181809, 2018). "Nevertheless, the molecular mechanisms underlying LOX-promoted ER– breast cancer metastasis and the best approach to treating LOX+ ER– breast cancer patients remains unknown." (PMID 27147578, 2016). "Since poly (ADP-ribose) polymerase (PARP) inhibitors are effective for treatment of breast cancer patients with BRCA1 mutation, this class of drugs may also be effective for managing breast cancer patients who overexpress LOX and carry BRCA1 mutation." (PMID 27147578, 2016). "Since BRCA1 mutation carriers are sensitive to PARP inhibitors, some LOX+ ER– breast cancer patients may also benefit from PARP inhibitors." (PMID 27147578, 2016). "Furthermore, increased LOX expression is associated with early stromal reaction in breast cancer, and reactive fibrosis at the invasive front of infiltrating tumors also releases high levels of LOX." (PMID 24338768, 2014). "Since ER is a routine diagnostic parameter in clinical breast cancer care, it may be worthwhile to analyse LOX expression in parallel to facilitate identification of patients belonging to this discrete subgroup with a very poor prognosis." (PMID 25141126, 2014). "The expression profile of LOXs, the putative associations among mRNA expression from each LOX and clinical observations, the correlation between expression of LOX enzymes and other genes, and the association between expression of LOXs and the tumour infiltrates were assessed for breast cancer." (PMID 35800439, 2022). "Thus, in breast cancer models, the crosslink between fibrosis-associated deposition of type I collagen and integrin β1 or lysyl oxidase (LOX), was described to create a growth-permissive microenvironment capable of reawakening DCCs, thus supporting proliferative metastatic growth." (PMID 33193295, 2020). "Chronic inflammation leads to collagen deposition and fibrosis associated with increased LOX expression and increased stromal collagen deposition has also long been recognised as a major contributing factor to the increased mammographic density that increases risk of breast cancer." (PMID 28077158, 2017). "Thus, the contribution of the LOX G473A SNP to breast cancer susceptibility may differ among populations." (PMID 25141126, 2014). "It clearly indicates that LOX research is closely intertwined with cancer, particularly breast cancer, the extracellular matrix, biological activation, and genetics." (PMID 40661776, 2025). "High LOX expression correlates with poor survival outcomes, particularly in breast cancer, where LOX-induced collagen crosslinking activates β1 integrin clustering, PI3K signaling, and focal adhesion formation, driving tumor progression." (PMID 41281748, 2025).
breast carcinoma (continued). "In a mouse model of breast cancer, estradiol supplementation affects lysyl oxidase activity, which in turn regulates collagen fiber formation and orientation." (PMID 40686616, 2025). "They showed that hypoxic breast cancer cells secrete LOX, which, upon circulation, cross-links Collagen IV in the lung basement membrane." (PMID 41463352, 2025). "Another study showed that bone marrow-derived MSCs enhance de novo production of lysyl oxidase in breast carcinoma cells, thus promoting Twist-induced EMT and increasing metastasis." (PMID 40083939, 2025). "The increased expression and secretion of lysyl-oxidase (LOX) by breast cancer cells results in the activation of HIF signaling." (PMID 38791951, 2024). "The silencing of Atox1 expression resulted in a decrease in LOX activity and inhibited the migration of breast cancer cells, indicating that ATOX1’s role in the ATP7A–LOX signaling pathway is associated with metastasis." (PMID 38918694, 2024). "LOX expression is positively correlated with matrix metalloproteinases (MMPs) and hypoxia-inducible factor 1α (HIF-1α), both of which are linked to breast cancer invasion and metastasis." (PMID 39247609, 2024). "Lysyl oxidase regulates breast cancer cell migration and adhesion through a hydrogen peroxide-mediated mechanism." (PMID 37469162, 2024). "By using LOX-RNAi-LV to transduce the MDA-MB-231 breast cancer cell line, researchers have observed a significant inhibition in the expression of MMP-2 and MMP-9, leading to reduced invasion and migration abilities of breast cancer cells." (PMID 39247609, 2024). "In summary, LOX is overexpressed in breast cancer, exerts oncogenic effects, and promotes cancer cell mobility and cancer progression by different manners." (PMID 39247609, 2024). "It has been discovered that LOX‐induced collagen cross‐linking increases the rigidity of the ECM in mouse breast cancer models, thereby inducing an integrin‐reliant invasive phenotype." (PMID 39164826, 2024). "A preclinical study of the aminomethiophene-based LOX inhibitor CCT365623 demonstrated that inhibition of LOX led to delayed tumor development and reduced lung metastasis in a mouse model of breast cancer." (PMID 39697341, 2024). "The copper chelator tetrathiomolybdate, which blocks the copper-dependent catalytic activity of LOX, is presently undergoing a phase II study (NCT00195091) involving patients with breast cancer at moderate to high risk of recurrence." (PMID 38238542, 2024). "MacroH2A1.2 reduces bone metastasis by attenuating the activity of lymphotoxin beta (LTβ) in prostate cancer and inhibiting secretion of lysyl oxidase (LOX) in breast cancer, thus exerting an anti-osteoclastogenic effect." (PMID 39199381, 2024). "This review will provide a theoretical basis and reference for clinical diagnosis and treatment of breast cancer, as well as for the screening of effective LOX-specific inhibitors." (PMID 39247609, 2024). "Lysyl oxidase (LOX) expression levels in dECM were essential for the diverse stiffness of breast cancer matrix and drug resistance." (PMID 38193110, 2024). "The EMT marker LOX has a differential expression pattern in breast cancer, the strong overexpression of LOX is more prevalent in triple-negative breast cancers than in non-triple-negative breast cancers (p<0.001)." (PMID 39247609, 2024). "In particular, the secretion of LOX by breast cancer cells in the lungs leads to the establishment of a premetastatic niche with bone marrow-derived cells (BMDCs) by restructuring collagen." (PMID 39247609, 2024). "In vitro models have shown that the production of LOX by mesenchymal stem cells leads to increased migration, metastasis, and resistance to anoikis of breast cancer cells." (PMID 39766266, 2024). "The utilization of a LOX inhibitor decreased metastatic formation using in vivo breast cancer models." (PMID 39766266, 2024).
breast carcinoma (continued). "Another study in breast cancer (BC) found that lysine oxidase (LOX), as an enzyme that catalyzes the cross-linking of collagen in extracellular matrix, can increase the matrix stiffness of BC by increasing the cross-linking of collagen." (PMID 38693304, 2024). "Preclinically, hampering LOX in breast cancer models in mice enhanced the therapeutic outcome of doxorubicin through a decrease in tissue stiffness." (PMID 38201302, 2024). "Decreasing the stiffness of tumor tissue by the administration of the matrix crosslinking enzyme lysyl oxidase (LOX) results in a marked decrease in blood vessel production in a mouse model of spontaneous mammary tumors." (PMID 38201302, 2024). "In a mouse model of breast cancer in situ, silencing of ATP7A inhibited the activity of LOX, thus rendering the LOX-dependent metastatic mechanism ineffective in breast cancer cell lines." (PMID 37427098, 2023). "By far the most findings with regard to the function of lysyl oxidase in tumour progression were obtained in the context of breast cancer." (PMID 37565736, 2023). "It has been shown that Lysyl oxidase is upregulated in breast cancer by recruiting MSCs to modulate breast cancer invasion, metastasis, and EMT." (PMID 38022534, 2023). "In breast cancer, not only is high expression of LOX related to bone metastasis, LOXL2 has also been shown to promote lung metastasis of breast cancer." (PMID 37767404, 2023). "β-Aminopropionitrile (BAPN), which is an irreversible suppressor of LOX, has anti-tumor effects in breast cancer, cervical cancer, anaplastic thyroid cancer, and ovarian cancer." (PMID 37509535, 2023). "β-Aminopropionitrile (BAPN) acts as a LOX inhibitor and suppresses breast cancer proliferation and metastasis by inhibiting collagen cross-linking." (PMID 37916166, 2023). "The earliest available drug is tetrathiomolybdate, which inhibits lung metastasis of head and neck tumors and breast cancer by reducing LOX activity." (PMID 37767404, 2023). "Degradation of breast cancer matrix is mainly dependent on the regulation of lysyl oxidase (LOX), lysyl oxidase like-1-4 (LOXL 1-4), and matrix metalloproteinases (MMPs), which are extracellular matrix remodeling enzymes." (PMID 37916166, 2023). "Copper pathways, including the ATOX–ATPase copper transporting Alpha (ATP7A)–lysyl oxidase (LOX) pathway, facilitate cancer cell metastasis, and inhibiting this pathway has been shown to impede breast cancer metastasis in vivo." (PMID 37886979, 2023). "Our study revealed consistent downregulation of the matrix processing protein LOX in premetastatic lungs as well as in breast cancer-conditioned lung fibroblasts." (PMID 37903851, 2023). "In breast cancer, LOX and collagen influence the architecture of the ECM and create a favorable microenvironment for tumor development and progression." (PMID 37916166, 2023). "For instance, it has been found that lysyl oxidase (LOX), which is an enzyme that crosslinks collagen and elastin, is overexpressed in many cancer tissues, such as gastric, colorectal, and breast cancer." (PMID 37190331, 2023). "It was shown that LOX-PP attenuates Her-2/neu-driven tumor development in a nude-mice breast-cancer model, via suppressing the ERK1/2, AKT, and NF-kB signaling pathways." (PMID 37298359, 2023). "Studies have shown that the prognostic model genes TK1, LOX, KDM5B, PSMD4, and NFE2L3 are associated with breast cancer progression, prognosis stratification, and clinical drug resistance." (PMID 37767092, 2023). "β-aminopropionitrile (β-APN) is a pan-LOX inhibitor that can suppress the migration and invasion of breast cancer cells." (PMID 35331296, 2022). "LOX derived from M2-like macrophages is also found to enhance breast cancer cells migration, and the LOX-induced migration is, likewise, inhibited by a H3K27 demethylase inhibitor." (PMID 35682926, 2022).